SERPINA1 (serpin family A member 1)
Description:
Inhibitor of serine proteases. Its primary target is elastase, but it also has a moderate affinity for plasmin and thrombin. Irreversibly inhibits trypsin, chymotrypsin and plasminogen activator. The aberrant form inhibits insulin-induced NO synthesis in platelets, decreases coagulation time and has proteolytic activity against insulin and plasmin. [Short peptide from AAT]: Reversible chymotrypsin inhibitor. It also inhibits elastase, but not trypsin. Its major physiological function is the protection of the lower respiratory tract against proteolytic destruction by human leukocyte elastase (HLE).
Synonyms: AAT; PI; A1A; PI1; alpha-1-antitrypsin; A1AT; alpha1AT; PRO2275; nNIF
Tractability: Small molecule: a structure with a bound ligand is known; it has a high-quality binding pocket. Antibody: its Gene Ontology location is reachable by antibodies, with high confidence; UniProt places it where antibodies can reach, with medium confidence; UniProt predicts a signal peptide or a membrane-spanning region. PROTAC: its protein half-life has been measured.
Gene: Protein-coding gene on chromosome 14 (94,376,745 to 94,390,866, reverse strand). Ensembl gene ENSG00000197249.
Subcellular location: Secreted; Endoplasmic reticulum; Secreted, extracellular space, extracellular matrix (Short peptide from AAT)
Subcellular location (Human Protein Atlas): Vesicles; Predicted to be secreted
Pathways (Reactome):
Metabolism of proteins: Post-translational protein phosphorylation; Regulation of Insulin-like Growth Factor (IGF) transport and uptake by Insulin-like Growth Factor Binding Proteins (IGFBPs)
Vesicle-mediated transport: COPII-mediated vesicle transport; Cargo concentration in the ER
Hemostasis: Platelet degranulation
Immune System: Neutrophil degranulation
Gene Ontology:
Molecular function: identical protein binding; protease binding; protein binding; serine-type endopeptidase inhibitor activity
Cellular component: endoplasmic reticulum; extracellular exosome; extracellular matrix; extracellular region; Golgi apparatus; COPII-coated ER to Golgi transport vesicle; endoplasmic reticulum lumen; endoplasmic reticulum-Golgi intermediate compartment membrane; ficolin-1-rich granule lumen; platelet alpha granule lumen
Genetic constraint (gnomAD): Loss-of-function variants: 22 observed, 27.71 expected, observed/expected ratio (o/e) 0.79, 90% interval 0.57 to 1.13. The upper end of that interval is the gene's LOEUF score, 1.13, which puts it in group 4 of 6, group 1 being the genes least tolerant of losing a copy. Missense variants: 546 observed, 535.69 expected, observed/expected ratio (o/e) 1.02, 90% interval 0.95 to 1.09. Synonymous variants: 218 observed, 218.18 expected, observed/expected ratio (o/e) 1, 90% interval 0.89 to 1.12.
Homologues: Orthologues: chimpanzee SERPINA1 (99% identical), macaque SERPINA1 (92% identical), dog SERPINA1 (75% identical), rat Serpina1 (69% identical), mouse Serpina1c (65% identical), mouse Serpina1a (64% identical), mouse Serpina1b (64% identical), rabbit SERPINA1 (64% identical), mouse Serpina1d (64% identical), mouse Serpina1e (63% identical), guinea pig Apf (63% identical), guinea pig Serpina3k (62% identical), and 1 more. Paralogues in human: SERPINA4 (44% identical), SERPINA2 (43% identical), SERPINA3 (43% identical), SERPINA11 (42% identical), SERPINA5 (41% identical), SERPINA6 (40% identical), SERPINA7 (40% identical), SERPINA9 (39% identical), SERPINA12 (38% identical), SERPINA10 (31% identical), SERPINB4 (30% identical), SERPINB9 (30% identical), and 24 more.
Diseases named in the same sentence as SERPINA1 in open-access papers:
SERPINA1 is named in the same sentence as 573 diseases in open-access papers, as found by Europe PMC text mining. Sharing a sentence is not in itself a finding about the gene and the disease. The quoted sentences say what the papers report.
emphysema (269 papers, 2004 to 2026). "Individuals homozygous for the SERPINA1 "Z" mutation with alpha-1 antitrypsin deficiency (AATD) are highly susceptible to emphysema." (PMID 41993529, 2026). "Mutations in SERPINA1 cause alpha-1-antitrypsin deficiency, one of the most common hereditary causes of respiratory disease, leading to early-onset emphysema and chronic obstructive pulmonary disease, as well as hepatic complications." (PMID 41800217, 2026). "As a protease inhibitor, SERPINA1 plays a vital role in tissue protection by neutralizing serine proteinases; its deficiency is known to contribute to emphysema and degenerative diseases." (PMID 41584047, 2026). "These include emphysema (SERPINA1 mutation), thrombosis (SERPINC1 deficiency), hereditary angioedema (SERPING1 deficiency), cirrhosis (SERPINA1 polymerization) and Alzheimer’s disease (SERPINA3 polymorphism)." (PMID 38966643, 2024). "For example, we found exotic variants in SERPINA1 gene which encode the protein associated with chronic obstructive pulmonary disease, emphysema, and chronic liver disease." (PMID 38491158, 2024). "Mutations in SERPINA1 are implicated in autoinflammatory diseases, including emphysema, liver cirrhosis, and skin panniculitis, as a result of over-activation of elastase and accumulation of mutant polymers." (PMID 36833193, 2023). "Studies have discovered that the point mutations in the SERPINA1 gene, which cause gain of function, lead to cirrhosis, whereas gain of function mutations causes pulmonary emphysema, a clinical condition comprising COPD." (PMID 36320441, 2022). "Chronic obstructive pulmonary disease (COPD), emphysema, PH, pulmonary fibrosis, and chronic liver disease are related to Serpina1 deficiency." (PMID 34805208, 2021). "A key target of SERPINA1 (alpha 1 antitrypsin) is elastase, and defects in the protein are associated emphysema." (PMID 32692488, 2020). "This theory is supported in vivo by the development of emphysema in hamsters receiving local administration of PR3 and further by recent evidence that SerpinA1-deficient murine models develop spontaneous emphysema." (PMID 30236095, 2018). "Deficiency and mutation of SERPINA1 can cause pulmonary emphysema via uncontrolled elastase activity and liver cirrhosis through accumulation of misfolded proteins and impaired secretion." (PMID 29206210, 2017). "For example, we identified evidence for the “collide” relationship for rs926144, an intergenic SNP in SERPINA1 (alpha-1-antitrypsin; AAT), a protein whose normal function is linked directly to the development of emphysema." (PMID 27532455, 2016). "Regarding the relatively high detection rate in 2003 – 2005, younger patients with emphysema have been tested, again a population more likely to carry a severe deficiency SERPINA1 genotype." (PMID 27282198, 2016). "In humans, SERPINA1 or alpha-1-antitrypsin plays a role in inhibition of neutrophil proteases and deficiency of SERPINA1 is linked to emphysema." (PMID 26710100, 2015). "This theory has been building up since the discovery of severe deficiency of a serine protease inhibitor Alpha-1-antitrypsin (encoded by SERPINA1 gene), which has been shown to predispose to early panlobular emphysema." (PMID 23734748, 2013). "Alpha-1 antitrypsin deficiency (AATD) results from mutations in the SERPINA1 gene and classically presents with early-onset emphysema and liver disease." (PMID 21752289, 2011). "A severe deficiency of alpha-1-antitrypsin, caused by mutations of the SERPINA1 (AAT) gene, causes premature and severe emphysema (OMIM 107400); however, SERPINA1 mutations explain only a small proportion of cases of COPD." (PMID 19300500, 2009). "However, these nominally associated SOMAmers included SERPINA1, which measures the level of alpha-1-antitrypsin, deficiency of which is a well-established causal determinant of impaired lung function via emphysema formation." (PMID 38238732, 2024).
emphysema (continued). "This study aimed to identify whether risk alleles of known genes linked with emphysema (SERPINA1) and pulmonary fibrosis (MUC5B) are associated with severe COVID-19, and whether plasma mucin 5B differs according to patients’ outcomes." (PMID 35892712, 2022). "We further speculate that AAT supplementation may delay the onset and progression of premature labor, similar to prophylactic treatment of emphysema associated with damaging SERPINA1 variants." (PMID 35477570, 2022). "SERPINA1 (AAT) deficiency and its polymerization may cause emphysema and cirrhosis." (PMID 40243422, 2025). "For example, emphysema and cirrhosis can be caused by deficiency and polymerisation of SERPINA1, respectively, thrombosis may be caused by polymerisation of SERPINC1, angioedema results from a deficiency of SERPING1 and familial dementia is a consequence of SERPINI1 polymerisation." (PMID 34198546, 2021). "Alpha 1 antitrypsin (A1AT) deficiency (A1ATD) is a common autosomal co-dominant genetic disorder caused by mutations on the SERPINA1 gene (chromosome 14) that may be clinically characterized by lung (emphysema, chronic obstructive pulmonary disease-COPD) and/or liver (cirrhosis) disease." (PMID 26446624, 2015). "The most important genetic factor related to the development of emphysema is AATD, which is caused by mutations in the SERPINA1 gene, resulting in reduced serum and tissue AAT levels, and therefore, insufficient inhibition of NE." (PMID 40472316, 2025). "Patients with AAT deficiency, caused by SERPINA1 mutations, experience chronic lung and liver condition, such as emphysema and chronic obstructive pulmonary disease." (PMID 39730062, 2024). "Meanwhile, human alpha-1-proteinase inhibitor, a potential targeting compound of SERPINA1, elicits a therapeutic effect on progressive ultimate fatal emphysema by inhibiting neutrophil elastase in the lung." (PMID 37324256, 2023). "In a family-based study of the rs28929474 variant (Z allele) in SERPINA1, which leads to alpha-1 antitrypsin deficiency (AATD) and greatly increased risk of emphysema, there was a significant genotype-by-smoking interaction on FEV1." (PMID 34913977, 2021). "Viral vectors have been designed to express genes that replace defective gene expression in patients with congenital disorders including alpha-1-antitrypsin (SERPINA1; A1AT) deficiency, a genetic serpin disorder, or serpinopathy, which causes severe emphysema." (PMID 32244484, 2020). "We questioned if a similar reduction in SERPINA1 gene expression can be observed in lung tissue from A1AT treated PiZZ emphysema patients as we found in hepatocyte cultures." (PMID 28486562, 2017). "SERPINA1 is a potent elastase inhibitor, the presence of which plays a critical role in controlling the protease cascade leading to tissue destruction and emphysema." (PMID 25767696, 2015). "Mutations in SERPINA1 gene cause AAT deficiency and predispose individuals to early-onset emphysema and liver diseases." (PMID 26141700, 2015). "The class of SERPINA1 variants termed "null" mutations lead to a complete absence of AAT production and while extremely rare, confer a particularly high risk of emphysema." (PMID 21752289, 2011). "Alpha-1 antitrypsin deficiency (AATD), caused by SERPINA1 mutations, may contribute to secondary SP (SSP) through mechanisms such as alveolar destruction and emphysema development." (PMID 41054037, 2025). "Administration of SerpinA1 is also suggested as a therapy for alpha-1-antitrypsin deficiency (AATD), in which there is an increased risk of emphysema, obstructive lung disease, and liver disease; however, it is unclear if AATD mutations are associated with COVID-19 severity." (PMID 38760690, 2024). "Interestingly, mice have six SERPINA1 paralogs (Serpina1a-f), which have been edited out to generate a model of A1AT deficiency and emphysema." (PMID 34784346, 2021).
emphysema (continued). "AATD may be associated with childhood and adult liver failure as well as early-onset pulmonary emphysema in the third to fourth decade of life and results from mutations in the SERPINA1 gene encoding AAT." (PMID 34276045, 2021). "We performed haplotype analyses for 5 adjacent SERPINA1 SNPs, but none of the haplotypes was found to be associated with emphysema (data not shown)." (PMID 21067581, 2010). "When comparing patients with and without SERPINA1 mutations, significant differences were observed in AAT serum levels, emphysema type (panlobular) and distribution (diffuse and lower-lobe predominant)." (PMID 41370566, 2025). "Augmentation therapy using supplementary SERPINA1 to elevate circulating levels in patients is the only approved therapy for AATD-related lung diseases, including chronic obstructive pulmonary diseases and emphysema." (PMID 38455847, 2023). "Although extraordinarily rare, SERPINA1 mutations that completely abolish AAT protein expression have been identified, and this absence of AAT leads to pulmonary emphysema and chronic bronchitis without liver disease." (PMID 35104244, 2022). "Recently, AAT-KO mice lacking all five Serpina1 paralogues were described to spontaneously develop emphysema with age and to exert an impaired lung antibacterial immunity but retain normal body weight, behavior, lifespan, and gender distribution." (PMID 36142337, 2022). "The first published report of a Null SERPINA1 mutation described the case of a 24 year old man who had advanced pulmonary emphysema and no detectable serum AAT." (PMID 25425243, 2014). "Likewise, A1AT KO mice spontaneously develop pulmonary emphysema with advancing age37,38, But as in the present study, young adult SerpinA1 KO mice have no abnormalities in the liver or lungs." (PMID 39532838, 2024). "Previous GWAS of COPD, emphysema, and lung function did not identify rs28929474 in SERPINA1." (PMID 30068317, 2018). "In addition, SERPINA1 mRNA was assessed in lung tissues from PiZZ emphysema patients with and without A1AT therapy, and in adherent human peripheral blood mononuclear cells (PBMC) isolated from healthy PiMM donors." (PMID 28486562, 2017).
liver disease (173 papers, 2005 to 2026). "Despite various polymorphisms in the SERPINA1 gene, clinically significant liver disease is primarily associated with the Z mutant allele and, to a lesser extent, the S mutant allele." (PMID 38397999, 2024). "In the Z allele, glutamic acid is replaced by lysine at position 342 of the SERPINA1 gene, and this mutation leads to the synthesis of a malformed protein, which can polymerize and accumulate in hepatocytes, potentially causing liver disease." (PMID 39661838, 2024). "Alpha-1 antitrypsin (A1AT) is a common genetic disease caused by a mutation in the SERPINA1 gene, predisposing patients to severe premature lung and liver disease." (PMID 38021884, 2023). "Our data reveal a relationship between intrahepatic accumulation of Z-AAT and alterations in lipid homeostasis, which implies that liver organoids provide an excellent model to study liver diseases related to the mutation of the SERPINA1 gene." (PMID 37569847, 2023). "TFEB gene transfer is a novel strategy for liver disease in SERPINA1 deficiency and prevent accumulation of toxic proteins." (PMID 34830348, 2021). "Homozygosity for the SERPINA1 Z allele causes α1-antitrypsin deficiency, a rare condition that can cause lung and liver disease." (PMID 33981765, 2021). "Even though, incidence of diseases caused by serpin polymerization is rare, homozygous mutations in SERPINA1 gene (α1 antitrypsin) is associated with liver disease including cirrhosis." (PMID 29159256, 2017). "Liver injury triggered by accumulation of mutant SERPINA1 in ER of hepatocytes is the most common genetic cause of hepatic disease in children." (PMID 25946105, 2015). "Severe Alpha-1 Antitrypsin (AAT) deficiency is a hereditary condition caused by mutations in the SERPINA1 gene, which predisposes to lung emphysema and liver disease." (PMID 25287719, 2014). "In humans, Serpin family A member 1 was associated with an increased risk of incident liver disease and was suggested to have a potential value for the diagnosis and prognosis of many human cancers being possibly involved in the immune regulation of the tumour microenvironment." (PMID 39795034, 2025). "Consequently, we recommend SERPINA1 genetic analysis in CVID patients at diagnosis in order to identify those with a higher risk for liver disease." (PMID 38791420, 2024). "Therefore, we recommend SERPINA1 genetic analysis in PAD in order to identify patients with a higher risk for liver disease." (PMID 38791420, 2024). "Moreover, we aimed to investigate the implications of SERPINA1 Pi∗S allele on the course of liver disease." (PMID 36176936, 2022). "Our data confirm the central role of PNPLA3 across the whole spectrum ofhile SERPINA1 risk alleles may be particularly relevant in the development of advanced fibrotic stages or for the decompensation of liver disease." (PMID 33804385, 2021). "Hence, our data that CSPH accumulates in patients with the SERPINA1 Z-allele confirm that this risk variant indeed has an influence on the progression of fibrosis at advanced stages of liver disease." (PMID 33804385, 2021). "As both of these variants seem to influence the progression of liver disease through different pathways, the question arose whether the strong association of SERPINA1 could be validated in an independent cohort." (PMID 33804385, 2021). "While many disease-causing SERPINA1 alleles exist, the most common pathological variant, the Z (Glu342Lys) allele, leads to the production of malfunctional AAT prone to polymerization and retention of polymers within hepatocytes followed by severe hepatic disease and hepatic failure in some cases." (PMID 34276045, 2021). "Organoids represent an innovative approach to validate specific genetic alterations in the SERPINA1 gene that are associated with liver disease development, and furthermore to identify and elucidate other genes associated with liver disease progression and to investigate putative treatments." (PMID 31832977, 2020).